ENSG00000221139
Synonyms: LOC124900410
Gene: Small nucleolar RNA gene on chromosome 18 (21,450,653 to 21,450,756, reverse strand). Ensembl gene ENSG00000221139.
Gene Ontology:
Biological process: RNA processing
Cellular component: nucleolus
Homologues: Orthologues: mouse Gm23839 (53% identical). Paralogues in human: SNORD23 (76% identical).